AURKA (aurora kinase A)
Diseases named in the same sentence as AURKA in open-access papers (continued):
Sharing a sentence is not in itself a finding about the gene and the disease.
cancer (continued). "Recent genomic profiling of about 3000 human cancer tissue specimens to identify various oncogenic signatures in The Cancer Genome Atlas project has reported that recurrent amplification and overexpression of Aurora kinase-A characterize distinct subsets of human tumors across multiple cancer types." (PMID 27933271, 2016). "Therefore, both AURKA and AURKB appear to be associated with malignant phenotypes of cancer and function as oncogenes." (PMID 27636990, 2016). "Correlation of overexpression of AURKA with malignant phenotypes has been shown in several cancers." (PMID 25625960, 2015). "In addition, the AURKA gene is frequently amplified and/or overexpressed in several types of cancer including those of the stomach and esophagus." (PMID 25593196, 2015). "MLN8237 is a potent inhibitor of AURKA that reduces the activity of AURKA in a variety of cancers." (PMID 24901229, 2014). "AURKA have been attractive targets for cancer treatment during past several years." (PMID 24025726, 2013). "Our studies indicate that hemizygous loss of HMMR/RHAMM, which occurs in approximately 50% of aggressive MPNST, may oncogene-addict tumours to AURKA activity and sensitize these cancers to AKI." (PMID 23328114, 2013). "When we dissociated spheres and re-seeded for a second passage, we found that the number of spheres formed was significantly reduced in the presence of MLN8237, which suggests that AURKA activity is necessary for the propagation and self-renewal of sphere-enriched cancer stem-like cells." (PMID 23328114, 2013). "Considering that AURKA can play a role in all these processes, our results further underscore its importance as a critical pharmacological target for preventing cancer progression." (PMID 22347440, 2012). "In various malignant tumors Aurora Kinase A had been found overexpression." (PMID 22809428, 2012). "PTPRD, as a natural antagonist of AURKA, might be of therapeutic value in cancers where its inactivation is epigentically reversible, such as in instances of promoter region hypermethylation." (PMID 22305495, 2012). "Expression of AURKA was detectable in all carcinomas and showed a unimodal distribution." (PMID 23186136, 2012). "Using multivariate Cox analysis adjusted to age, pTstage and histological grade, AURKA was also significantly associated with MFI in the ER+/HER2- but not in the ER-/HER2- carcinomas." (PMID 23186136, 2012). "Therefore, AURKA seems to reflect the degree of proliferation of carcinomas which is in agreement with its biological function in mitosis." (PMID 23186136, 2012). "AURKA was also associated with MFS in the molecular subtype ER+/HER2- carcinomas (HR 2.10; 95% CI 1.70–2.59; P<0.001), but not in ER-/HER2- nor in HER2+ carcinomas." (PMID 23186136, 2012). "In addition, nine isolates inhibited aurora kinase A, an anti-cancer related protein, and three inhibited caspase 3, a protein related to neurodegenerative diseases." (PMID 19370169, 2009). "In addition, 9 out of the 343 cytotoxic strains showed activity against aurora kinase A, a protein related to an indicator of anti-cancer activity." (PMID 19370169, 2009). "Deregulation of AURKA is known to have a role in cancer because AURKA regulates different cell cycle events, supporting centrosomes maturation and spindle assembly and stability; its over-expression was associated in MM with chromosomal instability and clinically aggressive disease." (PMID 19753302, 2009). "Consequently, AURKA has been identified as a potential target for cancer therapy." (PMID 39942770, 2025). "Therefore, AURKA has garnered widespread attention as a potential target for cancer treatment." (PMID 38673957, 2024). "Although we found that AURKA, as a ferroptosis-related gene, may be associated with cuproptosis-related genes such as DBT, DLST, LIAS, and PDHA1, how they interact with each other to influence cancer development needs to be investigated in depth." (PMID 38673957, 2024).
cancer (continued). "However, the extent of deregulated post-transcriptional events influencing AURKA expression across cancers is currently unknown." (PMID 39527514, 2024). "To evaluate whether AURKA overexpression is sufficient to yield high levels of nuclear AurkA, which have been reported as oncogenic in cancer cells, we used an hTERT RPE-1 cell line that we have generated for stable and inducible expression of exogenous myc-tagged AurkA." (PMID 36797043, 2023). "Additionally, we identified a hotspot at residue R371 of the AURKA structure that has the highest number of exclusively non‐cancer‐related pathogenic mutations and has not been previously discussed." (PMID 37572333, 2023). "Since AURKA-specific inhibitors show poor efficacy and a high degree of toxicity in clinical trials, the available inhibitors against Complex V functions could be a valuable resource for combinatorial therapies against AURKA and ATP5F1A or ATP5F1B in AURKA-related cancers in the upcoming future." (PMID 37386025, 2023). "AURKA could activate PI3K/AKT signaling pathway in various cancers." (PMID 36973424, 2023). "Notably, AURKA transcript levels were higher in most cancer tissues than in normal tissues." (PMID 36601056, 2022). "However, in other studies using cancer cells, hypoxia contrarily induced a down-regulation of AURKA expression, suggesting that the outcome on AURKA transcription in response to hypoxia might be tissue-specific." (PMID 36067794, 2022). "AURKA may play an essential role in the tumor microenvironment and tumor immunity, according to a pan-cancer analysis, and it has the potential to be a predictive biomarker for multiple cancers." (PMID 36685952, 2022). "Finally, we provided in vitro and in vivo evidence that the growth of cells and tumors that lack SOCS2-AS1 may be effectively blocked by AURKA inhibition, raising the possibility that SOCS2-AS1 loss in cancer cells may predict an anti-AURKA benefit." (PMID 33824269, 2021). "AURKA overexpression might participate in progressing cancers by blocking DNA damage repair." (PMID 34337875, 2021). "Furthermore, recent reports have mentioned that AURKA might have the potential to be considered as a therapeutic target in many types of cancers." (PMID 34337875, 2021). "Furthermore, due to the fact that AURKA exerts its function through specific substrates in certain cancers, inhibition of AURKA substrates instead of targeting AURKA kinase activity may decrease the adverse effects." (PMID 33451333, 2021). "This review introduces the cellular functions of AURKA, describes its identified interactions with synthetic lethal tumor suppressor partners, and discusses the latest developmental status of its inhibitors as potential candidates for precision cancer medicine." (PMID 34050264, 2021). "Therefore, the c‐Myc inhibitors could reduce the level of AURKA in cancers, and c‐Myc might be considered as a therapeutic target." (PMID 34337875, 2021). "Therefore, we speculated that the effect of the inhibitor and Si-AURKA on the cancer cells was offset by each other." (PMID 34702201, 2021). "Thus, it is tempting to speculate that the upregulation of mitotic kinases, including NEK2 and AURKA, frequently observed in many cancer types results in the gain of a nuclear function that directly or indirectly modulates the transcriptome of cancer cells." (PMID 34930366, 2021). "Even though the selective AURKA inhibitors might be less toxic than pan-inhibitors, it may also lead to drug resistance more easily, so it is necessary to develop broad Aurora kinase inhibitors to obtain drugs with greater potency for cancer treatment." (PMID 33451333, 2021). "Furthermore, ROC diagrams for this gene revealed that AURKA expression level could be an excellent biomarker for separating cancer cells from normal cells (p < 0.001)." (PMID 34337875, 2021).
cancer (continued). "However, since different cell/cancer types may express different systems for regulating AURKA transcription and the individual functions of SWI/SNF components can differ depending on the cell type, this model needs to be further investigated." (PMID 34050264, 2021). "As AURKA and Bora are overexpressed in several cancers and act as oncogenes, deciphering how AURKA is mechanistically activated by Bora in time and space may pave the way for the development of innovative therapeutic approaches that target only a subset of AURKA’s multiple biological functions." (PMID 33771996, 2021). "Consequently, the inhibition of EGFR or AURKA reverses the adaptation of cancer cells to ARS-1620." (PMID 34607583, 2021). "Phosphorylation by AURKA at Ser243 may account for the cancer-promoting effects of KCTD12." (PMID 33451333, 2021). "Therefore, DCCT inhibiting AURKA activity and thus, leading abnormal microtubule formation may be a promising drug candidate targeting AURKA in cancer therapy." (PMID 32978717, 2021). "Therefore, AURKA is an attractive target for cancer therapy." (PMID 33245732, 2020). "AURKA overexpression enhances cell survival by suppressing autophagy through activating the mammalian target of rapamycin (mTOR) signaling, activating anti-apoptosis signaling, and/or cancer cell survival and chemoresistance by activating of PI3K/Akt/GSK3 and NF-κB signaling cascades." (PMID 33353031, 2020). "Therefore, AURKA represents an attractive target for cancer therapeutics." (PMID 32127951, 2020). "Especially in the case of both HPRT1 and AURKA, it may be beneficial to develop therapies to reduce their expression, thereby determining whether these genes play a critical role in cancer survival and proliferation as they show significant impact on overall patient survival." (PMID 30679932, 2019). "Furthermore, AURKA could inhibit the apoptosis of cancer cells by decreasing pro-apoptotic modulators (Caspase-3, Bax) and increasing anti-apoptotic regulators (Bcl-2)." (PMID 31706255, 2019). "This means AURKA could help to fuel fast-growing cancer cells." (PMID 30070631, 2018). "Finally, the shortest path analysis added 8 connecting genes that may be relevant to explain how AURKA modulation may affect the activity of these pathways, and thereby further induce proliferation in developing carcinoma cells." (PMID 29760449, 2018). "Besides, AURKA could contribute to cancer cell survival via increasing anti-apoptotic modulators (Bcl-2, MCL-1) and decreasing pro-apoptotic regulators (Bax, Bim, PUMA) or suppressing autophagy through activating mammalian Target of Rapamycin (mTOR) signaling." (PMID 28147341, 2017). "Although we have not specifically investigated these pathways in the present study, it is plausible that targeting AURKA in CDDP‐resistant cancer models may induce cancer cell death not only through the suppression of eIF4E‐c‐MYC‐HDM2, but also through reversing these signaling effects." (PMID 28417568, 2017). "AURKA could phosphorylate RAS-association domain family 1, isoform A (RASSF1A), a novel tumor suppressor, disrupt RASSF1A-mediated microtubules stabilization and M-phase cell cycle arrest, and lead to uncontrolled proliferation in cancers." (PMID 28147341, 2017). "Consistent with this new role for AurkA in controlling the stem-like subpopulation through Wnt3a/β-catenin signaling, a direct consequence seems that AurkA may affect chemoresistance and recurrence in cancer patients." (PMID 27341528, 2016). "Hence, AURKA can be considered an oncogene and thus an important target for cancer therapy." (PMID 26036635, 2015). "Thus, the COP1-p27-Aurora kinase A link can be recapitulated in cancer samples." (PMID 25957415, 2015).
cancer (continued). "Furthermore, AURKA was shown to regulate pluripotency of embryonic stem cells, which may suggest that AURKA plays a role in regulating stemness features of cancer cells." (PMID 25987188, 2015). "Thus, over-expression of DLG7 and AURKA in cancers and in MM suggests that mis-regulation of this complex could play a role in carcinogenesis." (PMID 19753302, 2009). "AURKA expression was found to be elevated in both HBV-HCC and Cr-HCC cases, consistent with reports in various other cancer types." (PMID 41515655, 2026). "For the polar aqueous fraction, the hub proteins obtained by evaluating the overexpressed genes in the three types of cancer (BRCA, COAD, and LUAD) were TYMS, CDKN1, TOP2A, AURKA, and TK-1." (PMID 40430485, 2025). "In terms of CNAs, the cancer maintained the FGFR1 amplification and PIK3R1 deep deletion from the primary sample and acquired an amplification in AURKA in the metastatic sample." (PMID 40379787, 2025). "For other genes, the proportion changes in different cell types expressing BIRC5, CDK1, AURKA, E2F1, and KIF2C are remarkably similar to the overall proportion changes in different cell types during cancer progression." (PMID 39859485, 2025). "The differential expression patterns and drug sensitivity profiles of CYP1A2, AURKA, and ESR1 highlight their potential significance in the context of immune modulation and cancer therapy." (PMID 40864066, 2025). "CCNB1, PLK1, CDK1, BUB1B, AURKA, and NDC80 are genes involved in various stages of the cell cycle process, which is crucial from a cancer perspective." (PMID 40287845, 2025). "As expected, AURKA ablation significantly inhibited proliferation in all cell lines, whereas CDK2 and VPS37A knockout selectively suppressed growth in cancer cells." (PMID 40180891, 2025). "Aurora kinase A (AURKA) is a crucial mitotic kinase, and its activation plays important roles in a variety of cancers." (PMID 38521813, 2024). "For all the cancers, except PRAD and THCA, there existed a positive correlational relationship (r > 0.1) of varying degrees between AURKA mRNA and protein expression levels." (PMID 39527514, 2024). "Both AURKA and AURKB are frequently overexpressed in cancer, and involved in tumor formation and progression." (PMID 39198859, 2024). "Both AURKA and AURKB are known to be upregulated in many cancers and their expression has been shown to be regulated by the EWSR1/FLI1 fusion." (PMID 39518006, 2024). "Currently, some small-molecule drugs targeting AURKA and AURKB have been discovered for cancer treatment." (PMID 39045407, 2024). "Despite the frequent occurrence of AurkA/TPX2 co-overexpression in cancer, the investigation of their involvement in tumorigenesis and cancer therapy resistance mostly arises from studies focusing only on one at the time." (PMID 39195284, 2024). "More than ten years ago, we highlighted the frequent co-overexpression of AurkA and TPX2 in cancer, and proposed that it holds oncogenic potential, resulting in the formation of an oncogenic holoenzyme." (PMID 39195284, 2024). "Some evidence exists positively correlating AurkA overexpression with CIN in tumours and cancer cells." (PMID 39195284, 2024). "As both AURKA and SOX2 are overexpressed in numerous cancers, the impact of their potential crosstalk on aggressive oncogenic phenotypes remains a subject of huge interest." (PMID 39334449, 2024). "Aurora kinase A (AURKA) plays a crucial role in mitotic control and acts as an oncogene in various cancer types, including PCa." (PMID 39123360, 2024). "Mitotic kinases such as AURKA and AURKB have gained much attention as potential therapeutic targets against cancer, due to their essential role in the cell cycle, especially during mitosis." (PMID 38886738, 2024). "For example, we previously showed that hsa-let-7a targets only the long APA isoform of AURKA mRNA and a different short/long ratio (SLR) of AURKA APA isoforms is present between several types of normal and cancer cells." (PMID 39527514, 2024).
cancer (continued). "Additionally, exploring the synergistic effects of AURKA inhibition with its other oncogenic and/or tumor-suppressor targets could provide further opportunities for developing effective combination therapies against AURKA-driven cancers, thereby maximizing its potential as a critical drug target." (PMID 39334449, 2024). "Overexpression of AURKA and AURKB occurs in cancers of many origins, where they function as oncogenes to promote tumorigenesis and metastasis." (PMID 39334449, 2024). "Currently, some small-molecule drugs targeting AURKA and AURKB have been discovered for the treatment of cancer." (PMID 39045407, 2024). "However, abnormally expressed AURKA may act as an oncogene in a variety of cancers." (PMID 38287009, 2024). "One of the common themes that emerge is that AURKA is often involved in a feedback loop with its substrates, which could be the decisive factor causing its sustained upregulation and hyperactivation in cancer cells, an Achilles heel not exploited before." (PMID 39334449, 2024). "Since their identification, AurkA and TPX2 have been described as being overexpressed in cancer, with a significant correlation with highly proliferative and aneuploid tumours." (PMID 39195284, 2024). "It was reported that inhibition of AURKA significantly decreased the survival of luminal and HER-2 cancer models." (PMID 38606093, 2024). "In esophageal squamous-cell carcinoma (ESCC), the expression of GPX4 was downregulated by the knockdown of aurora kinase A (AURKA), which led to the activation of ferroptosis and suppression of cancer progression." (PMID 39125992, 2024). "Molecular dynamics simulations were conducted on three AURKA and AURKB systems bound by three inhibitors (HPM, MPY, and VX6) to gain insights into their binding selectivity for anti-cancer drug development." (PMID 38113210, 2023). "In terms of MSI, we observed a significant correlation between AURKA expression and the MSI score in specific cancers such as UCEC, ESCA, and SARC, while a low AURKA expression inversely correlated with MSI in DLBC (p<0.001)." (PMID 37965456, 2023). "Our analyses led to the identification of CDK1, CCNA2, CCNB1, AURKA, and EZH2 as signature genes involved in cancer stemness and progression." (PMID 37189841, 2023). "Out of these, AURKA, TOP2A, CDK1, and BUB1 were also included in the list of most frequent top NMF genes across the 24 cancer types." (PMID 37973839, 2023). "Our study provided a solid theoretical basis for the clinical translation of antitumor drugs targeting AURKA and extend the understanding of the importance of METTL 16 mediated m6A RNA modification in cancer biology." (PMID 37773181, 2023). "Based on the statistical analyses of the PPI network of upregulated genes, AURKA, AURKB, TTK, MELK, and KIF20A were also involved in module 1, indicating their importance both in primary tumorigenesis and cancer progression." (PMID 37231064, 2023). "Our analysis demonstrated a robust correlation between AURKA expression and CNV in most cancers, highlighting the widespread presence of AURKA and relevant CNV alterations in tumors." (PMID 37965456, 2023). "To date, a lot of APC substrates involved in cell cycle regulation have been demonstrated to be overexpressed in several cancer types, including CDC20, the Aurora A and B kinases (AURKA and AURKB, respectively) and Forkhead box M1 (FOXM1)." (PMID 37447165, 2023). "Several small-molecule inhibitors have successfully disrupted the interaction between N-MYC and AURKA, leading to the destabilization and degradation of N-MYC and subsequently tumor regression in MYCN amplified cancers." (PMID 36830089, 2023).